IL15 (interleukin 15)
Diseases named in the same sentence as IL15 in open-access papers (continued):
Sharing a sentence is not in itself a finding about the gene and the disease.
tumor (continued). "In the presence of pAgs, IL-15-cultured dendritic cells (DCs) significantly boost the anti-tumor activity of γδ T cells through the secretion of soluble IL-15." (PMID 39748921, 2024). "Here, we demonstrated in vitro and in vivo the therapeutic potential of IL-15 armored CD70-CAR NK cells to eliminate both CD70+ tumor cells and, most interestingly, also tumor-promoting CD70+ CAFs in CRC and PDAC." (PMID 38331849, 2024). "Persistence of immune cells can be improved by the transgenic delivery of IL-15 or IL-21 to optimize proliferation and persistence of tumor-reactive CD8+ memory T cells." (PMID 38475820, 2024). "Discerning the role of IL-15 in the regulation of anti-tumor immune responses for immunotherapeutic approaches against cancer, the data in this study suggest the importance of critical timing during tumor development for effective immunotherapy treatments." (PMID 39451257, 2024). "On the one hand, intracellular IL-15 promotes tumor cell migration and metastasis in vivo; on the other hand, extracellular IL-15 suppresses tumor progression by inhibiting tumor cell migration and enhancing antitumor immune responses." (PMID 38637902, 2024). "Cytokines released by T cells, such as IL-2 and IL-15, have been shown to activate NK cell cytotoxicity and enhance anti-tumor responses." (PMID 39221244, 2024). "γδ T cells stimulate immune responses indirectly by secreting cytokines like interferon-γ (IFN-γ), tumor necrosis factor-α (TNF-α), interleukin (IL)-2, IL-10, IL-12, and IL-15, impacting both tumor cells and the microenvironment." (PMID 39748921, 2024). "We then investigated PD effects of the IL-15 modules of GT-00AxIL15 on immune effector cells in tumor-free mice." (PMID 38338686, 2024). "Previous studies have demonstrated that the expression of membrane-bound IL-15/IL-15R fusion protein in NK cells significantly improved the activity and persistence of NK cells in vivo, ultimately enhancing their anti-tumor ability in mice." (PMID 39664387, 2024). "This combination treatment resulted in a higher local dosage of IL-15, induction of CAR T cell expansion, and improved in vivo tumor clearance when compared to systemic administration of free IL-15 and CAR T cells." (PMID 39030582, 2024). "Of all the evaluated myokines, tumour tissues showed higher expression levels only for IL-15 and myostatin." (PMID 39411315, 2024). "All mice treated with NK:BOB1-TCR/IL-15 showed a significant decrease in tumor burden directly after NK cell infusion compared with mice treated with NK:CMV-TCR/IL-15 and non-treated mice." (PMID 38690288, 2024). "The selection of cytokines was based on their significant role in regulating the tumor microenvironment, including promoting either the Th1 (IL-2RA, IL-12(p40), IL-15, TNF-α, IL-1β, IL-1RA, and IFN-γ) or the Th2 (IL-4, IL-6, IL-8, and IL-10) profile." (PMID 39768997, 2024). "CAR-T cells engineered to secrete IL-15 exhibit augmented tumor cytotoxicity, increased T cell expansion and persistence, and greater protection against tumor recurrence." (PMID 38904025, 2024). "Here, we show that sorted CD8α–CD56dim NK cells had superior tumor control in vivo, likely due to enhanced IL-15–induced proliferation." (PMID 38805302, 2024). "Together, these data point to potent IL-15 signaling, effector protein abundance, and a stable redox balance as critical factors for optimal tumor control by NK cells in severe hypoxia." (PMID 39475618, 2024). "Positive clinical outcome following CAR-NK cell therapy was recently published, highlighting how NK cells can be armed with a CAR for improved tumor targeting and with autocrine IL-15 production for improved in vivo persistence." (PMID 38769377, 2024). "Their results highlight the powerful anti-tumor potential of IL-15-based treatments combined with immune modulatory anti-MICA/B and anti-NKG2A for cancer treatment for which co-cultured spheroids deeply help to characterize the efficacy and mode of action." (PMID 39261955, 2024).
tumor (continued). "Surprisingly, even after almost 3 weeks in vivo in the presence of K562 tumor cells and high doses of IL-15, iCD8α+ NK cells had enhanced responses to K562 and cytokine stimulation compared with persistent CD8α– or sustained CD8α+ NK cells." (PMID 38805302, 2024). "Our study demonstrated for the first time that tumor cell-intrinsic IL-15 contributes to cancer cell aggressiveness, as evidenced by the promotion of cell migration and invasion." (PMID 38637902, 2024). "GT-00AxIL15 was shown to specifically bind TA-MUC1 on tumor cells via its mAb moiety, to IL-15 receptors on immune cells via its IL-15 fusion modules and to FcγRs via its functional Fc-part." (PMID 38338686, 2024). "IL-15 is another cytokine with therapeutic potential to promote anti-tumor immunity via its activity on NK and T-cells." (PMID 38515757, 2024). "The sustained proliferation of tumour-specific T cells can be maintained in the presence of IL-15, allowing the preparation of T cells on a clinical-use scale." (PMID 39215816, 2024). "Following tumor exposure, overnight IL-15 treatment leads to increased expression of NKG2D and IFN-γ, partially restoring production." (PMID 39221244, 2024). "Here, we show that a single IT injection of MS~RLI or IT MS~IL-15 resulted in moderate tumor growth inhibition but strong reduction of lung metastases." (PMID 39559362, 2024). "NKTR-255, a polymer-conjugated recombinant human interleukin-15 agonist, significantly stimulated NK cell proliferation and expansion and further enhanced the in vitro cytotoxic activity and in vivo anti-tumor efficacy of anti-MCAM-CAR-NK cells against NB." (PMID 39554906, 2024). "Mechanistic analysis revealed that both the intracellular and extracellular IL-15-mediated effects required the expression of IL-15Rα by tumor cells." (PMID 38637902, 2024). "Our results support the potential of GT-00AxIL15 as next-generation tumor-targeted IL-15-based immunocytokine for treatment of solid tumors." (PMID 38338686, 2024). "Immune activation in the periphery and lymphoid organs is actually the mechanism of action of nearly all other non-tumor-targeted IL-15 based immunocytokines, which show promising results in the clinic." (PMID 38338686, 2024). "The study has reported that T cells expanded in the presence of IL-15 had greater anti-tumour activity and eradicated established tumours in animal models." (PMID 39215816, 2024). "To further verify the antitumor activity of 12 C CAR-NK cells and the contribution of IL-15 to the efficacy in vivo, we established a mouse tumor model by tail intravenous injection of Jurkat-Luc cells." (PMID 39462383, 2024). "Interleukin (IL)‐15 has emerged as a promising candidate for enhancing CD8+ T‐cell mediated tumour eradication." (PMID 38279870, 2024). "Persistence is dependent upon the production at the tumor site of homeostatic cytokines such as IL-15 and the reduction of anti-proliferative signaling well exemplified by CPI therapy or epigenetic reprogramming of T cells to knock down CPI expression." (PMID 38475820, 2024). "The in vivo PK profile and IL-15-mediated PD effects of GT-00AxIL15 were investigated in tumor-free mice." (PMID 38338686, 2024). "Taken together, this explains how the low concentration of IFN-γ and IL-15 in M1 patients is correlated with tumor metastasis." (PMID 39768997, 2024). "In an overall, IL-15/IL-15Rα-NKG2D CAR-T cells (N15 CAR-T cell group) had the most satisfactory efficacy for inhibiting B-LCL tumor progression and EBV replication in mouse models." (PMID 39160631, 2024). "Our results demonstrated for the first time that IL-15 expressed by cancer cells functions as a double-edged sword in tumor progression." (PMID 38637902, 2024). "To date, fourth-generation CARs favor the secretion of cytokines (including IL-12 and IL-15) and thus strongly influence the immune components of the tumor microenvironment." (PMID 38570866, 2024).
tumor (continued). "The therapeutic strategy that combines TIGIT blockade with IL‐15 stimulation was verified using a transplanted tumour murine model and a patient‐derived organoid (PDO) model." (PMID 38279870, 2024). "Of all the remaining myokines, tumor tissues showed higher expression only for IL-15 and myostatin with relative abundance ratios of 2.4 and 3.1, respectively." (PMID 39411315, 2024). "Treatment with 10 μg IT MS~RLI resulted in a moderate ~42% TGI and a 76% reduction in terminal tumor weight, whereas equimolar MS~IL-15 gave only ~20% TGI and insignificant ~30% tumor weight reduction." (PMID 39559362, 2024). "It was shown that the use of GD2.CAR-T cells and OVs armed with the chemokine RANTES and IL15 directly accelerated caspase pathways in tumor-exposed T cells, with RANTES and IL15 promoting CAR-T recruitment to the tumor and ensuring their local survival." (PMID 38558810, 2024). "Preclinical studies have found that T cells cultured in IL15 or expressing IL15 showed excellent anti-tumor abilities in vivo." (PMID 39650651, 2024). "IL-15 was the choice of interleukin because it has previously been found to control tumor growth by improving the killing potential of NK cells and the proliferation of NK cells both in vitro and in vivo." (PMID 38496035, 2024). "GT-00AxIL15 is a novel immunocytokine designed to direct the highly potent immune cell stimulator IL-15 to the tumor and its microenvironment via its TA-MUC1-targeting mAb moiety thereby improving its PK/PD properties and anti-tumor efficacy." (PMID 38338686, 2024). "Our data suggest that although cancer cell-intrinsic IL-15 can promote metastasis, high expression of IL-15 in tumor cells increases the amount of IL-15 in the tumor microenvironment and enhances the efficacy of anti-PD-L1 immunotherapy." (PMID 38637902, 2024). "In a mouse model of pulmonary melanoma, MSCs were utilized to deliver an IL-15-carrying tumor-lytic MYXV construct, resulting in sustained viral presence and increased infiltration of NK cells and CD8+ T cells." (PMID 39055561, 2024). "The proinflammatory cytokines IL-15, IL-18, and IL-1β profiles reveal a significant host serum increase after day 35 when the tumor began to progress in growth." (PMID 39451257, 2024). "It will be helpful to further characterize iCD8α+CD56bright populations and their effect on tumor control, as IL-15–primed CD56bright NK cells can exhibit robust antitumor cytolytic activity." (PMID 39087476, 2024). "Among these, myostatin is associated with transforming growth factor-β, interleukin-15, NK cells, CD3, and CD8 T cells, all of which are linked to tumor progression." (PMID 38890682, 2024). "When co-cultured with BALL-1 cells, both NK cells and single-target CAR-NK cells exhibited elevated secretion levels of perforin, IFN-γ, and IL-15 in comparison to non-tumor-activated NK cells." (PMID 38475814, 2024). "The addition of cycloheximide (CHX), a widely used translation inhibitor, to the cell culture reversed the upregulation of vimentin expression in the IL-15-overexpressing tumor cells." (PMID 38637902, 2024). "The therapeutic potential of IL-15 in cancer treatment is highlighted by its capacity to alter the tumor microenvironment from one that supports tumor growth to one that is inhospitable to cancer cells." (PMID 38672104, 2024). "Next, using an identical experimental set-up to that used in the RNA-seq analysis, we treated B16F10 tumors with αCD45-Cyt or IgG-Cyt therapy and profiled p15E+CD8+ T cells in the tumor and TDLNs 24 h after IL-15 dosing by flow cytometry." (PMID 39112631, 2024). "Skeletal muscle plays a pivotal role in modulating the tumor microenvironment and influencing immunomodulation through the secretion of a variety of myokines, such as Irisin, IL-15." (PMID 38690276, 2024). "CAR-T cells that secrete IL-15 exhibit a superior capacity to eliminate tumor cells compared to other cytokines." (PMID 38402232, 2024).
tumor (continued). "Exercise training also increased IL‐6 and IL‐15 levels in the blood and altered the expression of apoptosis‐related proteins in tumor tissue, with the combined treatment group showing even more significant changes." (PMID 38234174, 2024). "IL-15 functions as an upstream regulator of tumor-infiltrating CD8+ T cells, and the IL-15/IL-15Rα+ axis plays a crucial role in anti-tumor immunity." (PMID 39055561, 2024). "Our results reveal that the addition of IL-15 to the NK:BOB1-TCR product increased its cytotoxic profile against TCR Ag positive tumor cells, indicating improved TCR-mediated cytotoxicity." (PMID 38690288, 2024). "Further enhancing the CAR-NK cell repertoire, researchers are investigating the application of IL-15 super agonist complexes, which hold the potential to significantly boost the survival, persistence, and anti-tumor efficacy of CAR-NK cells." (PMID 39199421, 2024). "GT-00AxIL-15 is an IL-15-based ICK targeting the tumor-specific, glycosylated epitope of MUC1 (TA-MUC1)." (PMID 39204319, 2024). "The injection of IL-15 enhanced the cytotoxic activity of NK cells, made them proliferate vigorously, and enhanced the anti-tumor effect." (PMID 39456138, 2024). "In IL-15 levels, little other than a small increase back to its previous peak and a significant decrease in tumor volume by the end of the trial was seen." (PMID 39451257, 2024). "Autologous CD8+ TILs, isolated from patient tumour tissues, were cocultured with the PDOs and subsequently treated with IL‐15, anti‐TIGIT, or their combination." (PMID 38279870, 2024). "Depletion of CD8 T cells in combination with IL-15:IL-15Ra complexes improved tumor control versus PBS/anti-CD8α Abs, consistent with a distinct NK cell and CD8 T cell contribution to anti-tumor responses." (PMID 38267402, 2024). "For example, IL-15 is a key cytokine for NK cell development and maintenance and has been shown to enhance the anti-tumor efficacy of CAR-NK cells in preclinical models." (PMID 39199421, 2024). "We will further modify the CD19 CAR-UESC to obtain CD19 CAR-UiNK cells that ectopic production of IL-15, thereby enhancing their in vivo proliferation, persistence, and anti-tumor activity." (PMID 39664387, 2024). "A single dose of CAR-DOT cells in combination with IL-15, achieved robust tumor control even after rechallenge." (PMID 39748921, 2024). "The intercellular level of IL-15 and density of tumor-infiltrating CD8 + T lymphocytes were greater in Lv-mIL-15-transfected LLC tumors than in control LLC tumors." (PMID 38637902, 2024). "Tumor-bearing mice were treated with IL-12/15/18–preactivated NK cells and IL-15–pretreated NK cells." (PMID 39020411, 2024). "The cytokine IL-15 is produced by a broad range of cells including pAPCs, stromal cells, endothelial cells and tumour cells, and acts through the IL-15 receptor (IL-15R)." (PMID 38745765, 2024). "Relative tissue myokine expression evaluated by the LC-MS/MS method showed increased tumor levels only for IL-15 and myostatin, arguing against the possibility of increased production of cachexia related mediators within the tumor." (PMID 39411315, 2024). "Next, using a murine LLC metastasis model, we evaluated the role of tumor cell-intrinsic IL-15 in regulating metastasis in immunocompetent mice." (PMID 38637902, 2024). "The anti-tumor properties of IL-2 and IL-15 have been reported, and IL-15 has been highlighted as a potential biomarker and therapeutic target in CRC." (PMID 39456247, 2024). "Expression of genes coding for NK-cell receptors including NCR3 (NKp30) in the malignant T cells was present in five patients, which can be explained either by enhanced Myc signaling or high IL15 expression in the tumor microenvironment." (PMID 39169943, 2024). "GT-00AxIL15 is a novel interleukin-15-based immunocytokine targeting a tumor-specific, glycosylated epitope of MUC1 (TA-MUC1)." (PMID 38338686, 2024).
tumor (continued). "Interleukin-15 plays an important antitumor role in tumor cell differentiation by inducing T immunotherapy and proliferation." (PMID 38279145, 2024). "ILC1s are potent producers of the well-established anti-tumour cytokine interferon γ (IFNγ), and exert direct cytotoxicity against cancer cells in response to the cytokine interleukin-15 (IL-15)." (PMID 38745765, 2024). "IL-15 demonstrated potent anti-tumor efficacy in mouse models; however, recombinant IL-15 clinical efficacy has been limited due to a short half-life and toxicities associated with systemic immune activation." (PMID 38315680, 2024). "It was also discovered that IL-15 enhances the survival, proliferation, and cytotoxicity of NK cells, resulting in improved anti-tumor capabilities." (PMID 38545115, 2024). "An additional potential target arising from this study was GM-CSF (granulocyte-macrophage colony-stimulating factor), which promoted tumor cell–macrophage interaction and the induction of resistance to IL-15." (PMID 37296860, 2023). "IL-15 has been shown to have a pro-tumorigenic role and is related to tumor escape, aggressive tumor behavior, and proinflammatory signaling." (PMID 36831406, 2023). "Memory-like NK cells (MLNK) induced by IL-12, IL-15, and IL-18 have shown enhanced and prolonged responses to tumor re-stimulation, making them an attractive candidate for adoptive cellular immunotherapy." (PMID 37207215, 2023). "This study demonstrates that gene-based delivery of IL-15/IL-15Rα to tumor cells effectively mediates anti-tumor activity and sensitizes the tumor microenvironment for therapy with αPD-L1 therapeutics mainly by impacting NK cells." (PMID 37923822, 2023). "On their arrival to the tumor site NK cells get activated by soluble (e.g. IL-2, IL-15, TNF-α, and IFN-γ) and contact-dependent signals from the tumor microenvironment (TME)." (PMID 37841273, 2023). "Second-generation TriKEs have been developed, with modifications to incorporate wildtype IL-15 to improve NK-specific proliferation and tumor control." (PMID 37514187, 2023). "The bioluminescence intensities and primary tumor growth of mice treated with IL-15 exhibited a slight reduction." (PMID 37875481, 2023). "Treatment with NIL-IM-Lip+L gave tumours with smaller volumes than IR780 + 1-MT + IL-15 + L (P < 0.001) and IL-IM-Lip+L (P < 0.01) treatment." (PMID 37076492, 2023). "Accordingly, the expression of IL-15 was significantly up-regulated in pancreatic xenograft tumor tissues, confirming the tumor-specific migration ability of MSCs-IL-15." (PMID 36742134, 2023). "Another next generation drug of IL-15 in preclinical trials is tumor-conditional IL-15 pro-cytokine (Pro-IL-15), designed by the team of Professor Fu Yangxin of Tsinghua University." (PMID 36936961, 2023). "We analyzed a tissue microarray to find possible correlations between intra-cellular expression of IL-15 and tumor stage and evolution." (PMID 37334356, 2023). "Expression of the membrane-bound form of IL-15 in human PB-derived NK cells has been shown to improve NK cell survival and in vivo anti-tumor activity." (PMID 37539051, 2023). "In the present study, we aimed to further investigate the potential of IL-15 release on tumor inhibition." (PMID 37585912, 2023). "Another crucial cytokine is IL15, which plays a pleiotropic role in improving the immune response to tumor cells and in the development, homeostasis, activation, and survival of T cells, natural killer cells (NK), and NK-T cells." (PMID 38067356, 2023). "Activation of IL-15 signaling in corresponding murine progenitor cells was shown to suppress tumor-growth in vivo after adoptive transfer." (PMID 36911660, 2023). "Stimulating NK cells with homeostatic and/or pro-inflammatory cytokines such as IL-2 and IL-15 enhances their effector functions, promotes anti-tumor immunity, and increases their persistence in the body." (PMID 38239346, 2023).